HMGB1 (high mobility group box 1)
Description:
Multifunctional redox sensitive protein with various roles in different cellular compartments. In the nucleus is one of the major chromatin-associated non-histone proteins and acts as a DNA chaperone involved in replication, transcription, chromatin remodeling, V(D)J recombination, DNA repair and genome stability. Proposed to be an universal biosensor for nucleic acids. Promotes host inflammatory response to sterile and infectious signals and is involved in the coordination and integration of innate and adaptive immune responses. In the cytoplasm functions as a sensor and/or chaperone for immunogenic nucleic acids implicating the activation of TLR9-mediated immune responses, and mediates autophagy. Acts as a danger-associated molecular pattern (DAMP) molecule that amplifies immune responses during tissue injury. Released to the extracellular environment can bind DNA, nucleosomes, IL-1 beta, CXCL12, AGER isoform 2/sRAGE, lipopolysaccharide (LPS) and lipoteichoic acid (LTA), and activates cells through engagement of multiple surface receptors. In the extracellular compartment fully reduced HMGB1 (released by necrosis) acts as a chemokine, disulfide HMGB1 (actively secreted) as a cytokine, and sulfonyl HMGB1 (released from apoptotic cells) promotes immunological tolerance. Has proangiogdenic activity (By similarity). May be involved in platelet activation (By similarity). Binds to phosphatidylserine and phosphatidylethanolamide (By similarity). Bound to RAGE mediates signaling for neuronal outgrowth (By similarity). May play a role in accumulation of expanded polyglutamine (polyQ) proteins such as huntingtin (HTT) or TBP. Nuclear functions are attributed to fully reduced HGMB1. Associates with chromatin and binds DNA with a preference to non-canonical DNA structures such as single-stranded DNA, DNA-containing cruciforms or bent structures, supercoiled DNA and ZDNA. Can bent DNA and enhance DNA flexibility by looping thus providing a mechanism to promote activities on various gene promoters by enhancing transcription factor binding and/or bringing distant regulatory sequences into close proximity. May have an enhancing role in nucleotide excision repair (NER) (By similarity). However, effects in NER using in vitro systems have been reported conflictingly. May be involved in mismatch repair (MMR) and base excision repair (BER) pathways. May be involved in double strand break repair such as non-homologous end joining (NHEJ) (By similarity). Involved in V(D)J recombination by acting as a cofactor of the RAG complex: acts by stimulating cleavage and RAG protein binding at the 23 bp spacer of conserved recombination signal sequences (RSS) (By similarity). In vitro can displace histone H1 from highly bent DNA (By similarity). Can restructure the canonical nucleosome leading to relaxation of structural constraints for transcription factor-binding (By similarity). Enhances binding of sterol regulatory element-binding proteins (SREBPs) such as SREBF1 to their cognate DNA sequences and increases their transcriptional activities (By similarity). Proposed to be involved in mitochondrial quality control and autophagy in a transcription-dependent fashion implicating HSPB1; however, this function has been questioned (By similarity). Can modulate the activity of the telomerase complex and may be involved in telomere maintenance (By similarity). In the cytoplasm proposed to dissociate the BECN1:BCL2 complex via competitive interaction with BECN1 leading to autophagy activation. Involved in oxidative stress-mediated autophagy. Can protect BECN1 and ATG5 from calpain-mediated cleavage and thus proposed to control their proautophagic and proapoptotic functions and to regulate the extent and severity of inflammation-associated cellular injury (By similarity). In myeloid cells has a protective role against endotoxemia and bacterial infection by promoting autophagy (By similarity). Involved in endosomal translocation and activation of TLR9 in response to CpG-DNA in macrophages (By similarity). In the extracellular compartment (following either active secretion or passive release) involved in regulation of the inflammatory response. Fully reduced HGMB1 (which subsequently gets oxidized after release) in association with CXCL12 mediates the recruitment of inflammatory cells during the initial phase of tissue injury; the CXCL12:HMGB1 complex triggers CXCR4 homodimerization. Induces the migration of monocyte-derived immature dendritic cells and seems to regulate adhesive and migratory functions of neutrophils implicating AGER/RAGE and ITGAM (By similarity). Can bind to various types of DNA and RNA including microbial unmethylated CpG-DNA to enhance the innate immune response to nucleic acids. Proposed to act in promiscuous DNA/RNA sensing which cooperates with subsequent discriminative sensing by specific pattern recognition receptors (By similarity). Promotes extracellular DNA-induced AIM2 inflammasome activation implicating AGER/RAGE. Disulfide HMGB1 binds to transmembrane receptors, such as AGER/RAGE, TLR2, TLR4 and probably TREM1, thus activating their signal transduction pathways. Mediates the release of cytokines/chemokines such as TNF, IL-1, IL-6, IL-8, CCL2, CCL3, CCL4 and CXCL10. Promotes secretion of interferon-gamma by macrophage-stimulated natural killer (NK) cells in concert with other cytokines like IL-2 or IL-12. TLR4 is proposed to be the primary receptor promoting macrophage activation and signaling through TLR4 seems to implicate LY96/MD-2. In bacterial LPS- or LTA-mediated inflammatory responses binds to the endotoxins and transfers them to CD14 for signaling to the respective TLR4:LY96 and TLR2 complexes. Contributes to tumor proliferation by association with ACER/RAGE (By similarity). Can bind to IL1-beta and signals through the IL1R1:IL1RAP receptor complex. Binding to class A CpG activates cytokine production in plasmacytoid dendritic cells implicating TLR9, MYD88 and AGER/RAGE and can activate autoreactive B cells. Via HMGB1-containing chromatin immune complexes may also promote B cell responses to endogenous TLR9 ligands through a B-cell receptor (BCR)-dependent and ACER/RAGE-independent mechanism (By similarity). Inhibits phagocytosis of apoptotic cells by macrophages; the function is dependent on poly-ADP-ribosylation and involves binding to phosphatidylserine on the cell surface of apoptotic cells (By similarity). In adaptive immunity may be involved in enhancing immunity through activation of effector T cells and suppression of regulatory T (TReg) cells. In contrast, without implicating effector or regulatory T-cells, required for tumor infiltration and activation of T-cells expressing the lymphotoxin LTA:LTB heterotrimer thus promoting tumor malignant progression (By similarity). Also reported to limit proliferation of T-cells (By similarity). Released HMGB1:nucleosome complexes formed during apoptosis can signal through TLR2 to induce cytokine production. Involved in induction of immunological tolerance by apoptotic cells; its pro-inflammatory activities when released by apoptotic cells are neutralized by reactive oxygen species (ROS)- dependent oxidation specifically on Cys-106. During macrophage activation by activated lymphocyte-derived self apoptotic DNA (ALD-DNA) promotes recruitment of ALD-DNA to endosomes (By similarity). (Microbial infection) Critical for entry of human coronaviruses SARS-CoV and SARS-CoV-2, as well as human coronavirus NL63/HCoV-NL63. Regulates the expression of the pro-viral genes ACE2 and CTSL through chromatin modulation. Required for SARS-CoV-2 ORF3A-induced reticulophagy which induces endoplasmic reticulum stress and inflammatory responses and facilitates viral infection. (Microbial infection) Associates with the influenza A viral protein NP in the nucleus of infected cells, promoting viral growth and enhancing the activity of the viral polymerase. (Microbial infection) Promotes Epstein-Barr virus (EBV) latent-to-lytic switch by sustaining the expression of the viral transcription factor BZLF1 that acts as a molecular switch to induce the transition from the latent to the lytic or productive phase of the virus cycle. Mechanistically, participates in EBV reactivation through the NLRP3 inflammasome. (Microbial infection) Facilitates dengue virus propagation via interaction with the untranslated regions of viral genome. In turn, this interaction with viral RNA may regulate secondary structure of dengue RNA thus facilitating its recognition by the replication complex.
Synonyms: HMG-1; HMG1; HMG3; SBP-1; DKFZp686A04236
Tractability: Small molecule: a high-quality ligand is known. Antibody: UniProt places it where antibodies can reach, with high confidence; its Gene Ontology location is reachable by antibodies, with high confidence. PROTAC: ubiquitination databases record sites on it; its protein half-life has been measured; a small molecule that binds it is known. Other modalities: a drug acting on it is in phase 2 or 3 trials.
Gene: Protein-coding gene on chromosome 13 (30,456,704 to 30,618,872, reverse strand). Ensembl gene ENSG00000189403.
Subcellular location: Nucleus; Chromosome; Cytoplasm; Secreted; Cell membrane; Endosome; Endoplasmic reticulum-Golgi intermediate compartment; Endoplasmic reticulum
Subcellular location (Human Protein Atlas): Nucleoplasm; Predicted to be secreted
Pathways (Reactome):
Immune System: Advanced glycosylation endproduct receptor signaling; ER-Phagosome pathway; MyD88:MAL(TIRAP) cascade initiated on plasma membrane; Neutrophil degranulation; Regulation of TLR by endogenous ligand; TAK1-dependent IKK and NF-kappa-B activation; TRAF6 mediated NF-kB activation
Disease: IRAK4 deficiency (TLR2/4); MyD88 deficiency (TLR2/4)
Programmed Cell Death: Apoptosis induced DNA fragmentation; Pyroptosis
Vesicle-mediated transport: Scavenging by Class B Receptors
Gene Ontology:
Molecular function: C-X-C chemokine binding; damaged DNA binding; DNA binding, bending; DNA polymerase binding; DNA-binding transcription factor binding; endodeoxyribonuclease activator activity; integrin binding; lipopolysaccharide binding; lyase activity; phosphatidylserine binding; protein binding; receptor ligand activity; RNA binding; RNA polymerase II-specific DNA-binding transcription factor binding; transcription cis-regulatory region binding; transcription coactivator activity; transcription corepressor activity; bubble DNA binding; chemoattractant activity; cytokine activity; double-stranded DNA binding; four-way junction DNA binding; RAGE receptor binding; single-stranded DNA binding; supercoiled DNA binding; and 5 more
Biological process: activation of innate immune response; apoptotic cell clearance; heterochromatin formation; inflammatory response; inflammatory response to antigenic stimulus; negative regulation of apoptotic cell clearance; negative regulation of blood vessel endothelial cell migration; negative regulation of CD4-positive, alpha-beta T cell differentiation; negative regulation of RNA polymerase II transcription preinitiation complex assembly; negative regulation of transcription by RNA polymerase II; negative regulation of type II interferon production; neutrophil clearance; positive regulation of activated T cell proliferation; positive regulation of apoptotic process; positive regulation of autophagy; positive regulation of blood vessel endothelial cell migration; positive regulation of chemokine (C-X-C motif) ligand 2 production; positive regulation of cytosolic calcium ion concentration; positive regulation of dendritic cell differentiation; positive regulation of DNA binding; positive regulation of ERK1 and ERK2 cascade; positive regulation of interleukin-1 production; positive regulation of interleukin-10 production; positive regulation of interleukin-12 production; positive regulation of interleukin-6 production; and 53 more
Cellular component: alphav-beta3 integrin-HMGB1 complex; cell surface; condensed chromosome; cytoplasm; endoplasmic reticulum; extracellular region; nucleoplasm; nucleus; plasma membrane; transcription repressor complex; chromosome; ficolin-1-rich granule lumen; secretory granule lumen; early endosome; endoplasmic reticulum-Golgi intermediate compartment; endosome; neuron projection
Genetic constraint (gnomAD): Loss-of-function variants: 0 observed, 17.77 expected, observed/expected ratio (o/e) 0, 90% interval 0 to 0.17. The upper end of that interval is the gene's LOEUF score, 0.17, which puts it in group 1 of 6, group 1 being the genes least tolerant of losing a copy. Missense variants: 74 observed, 204.72 expected, observed/expected ratio (o/e) 0.36, 90% interval 0.3 to 0.44. Synonymous variants: 65 observed, 68.75 expected, observed/expected ratio (o/e) 0.95, 90% interval 0.77 to 1.16.
Homologues: Orthologues: guinea pig Hmgb1 (100% identical), macaque HMGB1 (100% identical), rabbit HMGB1 (100% identical), mouse Hmgb1 (99% identical), rat Hmgb1 (99% identical), rat Hmgb1-ps34 (99% identical), rat Hmgb1l5 (97% identical), rat Hmgb1l2 (96% identical), rat AABR07029613.1 (93% identical), rat Hmgb1l1 (90% identical), tropical clawed frog hmgb1 (85% identical), zebrafish hmgb1a (74% identical), and 4 more. Paralogues in human: HMGB1P1 (93% identical), HMGB2 (77% identical), HMGB3 (68% identical), HMGB4 (35% identical), UBTF (33% identical), SSRP1 (27% identical), TOX2 (27% identical), TOX3 (25% identical), TOX (25% identical), TOX4 (25% identical), HMGXB4 (21% identical), SP100 (20% identical), and 8 more.
Diseases named in the same sentence as HMGB1 in open-access papers:
HMGB1 is named in the same sentence as 843 diseases in open-access papers, as found by Europe PMC text mining. Sharing a sentence is not in itself a finding about the gene and the disease. The quoted sentences say what the papers report.
Sepsis (905 papers, 2006 to 2026). Sepsis is defined as life-threatening organ dysfunction caused by a dysregulated host response to infection. "For instance, the release of HMGB1 during sepsis-induced AKI in rats is associated with a marked rise in pro-inflammatory factors emphasizing its contribution to inflammation." (PMID 40727103, 2025). "HMGB1 expression is substantially increased during polymicrobial sepsis, which is associated with a poor prognosis." (PMID 40624022, 2025). "In chronic kidney disease (CKD), impaired HMGB1 clearance further amplifies its pathogenic role during sepsis, exacerbating S-AKI severity." (PMID 40727103, 2025). "Consistent with our findings in LPS shock, hepatocyte GSDMD-mediated HMGB1 contributed to endothelial GSDMD-mediated systemic vascular damage in sepsis, and endothelial Gsdmd deficiency prevented sepsis-induced lethality." (PMID 39927458, 2025). "TLR4 also interacts with CD14, damage-associated molecular patterns (e.g., HMGB1), and NETs, amplifying inflammatory and coagulation pathways that link thrombocytopenia and sepsis progression." (PMID 40003683, 2025). "HMGB1 is implicated as a key extracellular mediator in severe vascular inflammatory diseases and sepsis." (PMID 40430897, 2025). "The link between HMGB1 and sepsis is also reflected in the close association with septic organ damage." (PMID 39963819, 2025). "In conclusion, this study confirmed that the APACHE II score, NT-proBNP, sTREM-1, and HMGB1 were independent risk factors for SIMD in patients with sepsis." (PMID 41477644, 2025). "In this study, we investigate the ability of CDDO-imidazolide, a potent Nrf2 activator, to regulate AM pyroptosis and HMGB1 secretion in sepsis-associated ARDS, along with its underlying mechanism." (PMID 40599023, 2025). "Elevated APACHE II score and NT-proBNP, sTREM-1, and HMGB1 levels are risk factors for SIMD in patients with sepsis." (PMID 41477644, 2025). "HMGB1 is closely associated with various modes of cell death in sepsis, and its role in skeletal muscle atrophy is significant." (PMID 39963819, 2025). "HMGB1 reacts with toll like receptors, leading to endocrine dysfunction causing insulin resistance and impaired glucose metabolism during sepsis." (PMID 39838305, 2025). "Across diverse AKI contexts, including sepsis, ischemia-reperfusion injury, nephrotoxin exposure, and contrast, HMGB1 has demonstrated significant diagnostic and prognostic utility." (PMID 40727103, 2025). "We further identified the underlying mechanism of the HMGB1/RAGE signaling pathway in vascular damage in sepsis." (PMID 39927458, 2025). "HMGB1 acetylation is essential for its cytoplasmic translocation and extracellular release from renal cells, promoting the progression of sepsis-associated AKI (SA-AKI)." (PMID 40727103, 2025). "EGCG can attenuate the progression of sepsis; the rapid progression in sepsis is associated with the release of high mobility group box-1 protein (HMGB1)." (PMID 39925527, 2025). "Early clinical studies concluded that in sepsis patients, HMGB1 also peaks late and associates with the severity of organ dysfunction, but it cannot distinguish between survivors and non-survivors." (PMID 40429966, 2025). "Silencing HMGB1 restores the protective effects of circTLK1 knockdown diminished by the miR-106a-5p inhibition, underscoring the pivotal role of the circTLK1–miR-106a-5p–HMGB1 regulatory axis in sepsis-associated AKI." (PMID 40727103, 2025). "The release of HMGB1 is closely associated with the inflammatory response, organ dysfunction and mortality in patients with sepsis." (PMID 39963819, 2025). "To conclude, HMGB1 is implicated in pathologies ranging from traumatic brain injury to neurodegenerative disease and is likely involved in sepsis-associated encephalopathy." (PMID 41226481, 2025). "It highlights HMGB1’s central role in sepsis-associated AKI, ischemia-reperfusion injury, cisplatin-induced nephrotoxicity, and contrast-induced nephropathy." (PMID 40727103, 2025).